TIPE3 (TNF alpha induced protein 8 like 3)
Description:
Acts as a lipid transfer protein. Preferentially captures and shuttles two lipid second messengers, i.e., phosphatidylinositol 4,5-bisphosphate and phosphatidylinositol 3,4,5-trisphosphate and increases their levels in the plasma membrane. Additionally, may also function as a lipid-presenting protein to enhance the activity of the PI3K-AKT and MEK-ERK pathways. May act as a regulator of tumorigenesis through its activation of phospholipid signaling.
Synonyms: TNFAIP8L3; FLJ41287
Tractability: Antibody: UniProt places it where antibodies can reach, with medium confidence; its Gene Ontology location is reachable by antibodies, with medium confidence. PROTAC: ubiquitination databases record sites on it.
Gene: Protein-coding gene on chromosome 15 (51,056,598 to 51,105,276, reverse strand). Ensembl gene ENSG00000183578.
Subcellular location: Cytoplasm; Cell membrane
Subcellular location (Human Protein Atlas): Cytosol; Nucleoplasm
Pathways (Reactome):
Metabolism: PI Metabolism
Gene Ontology:
Molecular function: protein binding; phosphatidylinositol binding; phosphatidylinositol transfer activity
Biological process: 1-phosphatidyl-1D-myo-inositol 4,5-bisphosphate metabolic process; phospholipid metabolic process; phospholipid transport; positive regulation of ERK1 and ERK2 cascade; regulation of intracellular signal transduction; intermembrane lipid transfer; regulation of apoptotic process
Cellular component: cytoplasm; cytosol; plasma membrane
Genetic constraint (gnomAD): Loss-of-function variants: 7 observed, 10.62 expected, observed/expected ratio (o/e) 0.66, 90% interval 0.37 to 1.24. The upper end of that interval is the gene's LOEUF score, 1.24, which puts it in group 5 of 6, group 1 being the genes least tolerant of losing a copy. Missense variants: 219 observed, 256.82 expected, observed/expected ratio (o/e) 0.85, 90% interval 0.76 to 0.95. Synonymous variants: 98 observed, 104.02 expected, observed/expected ratio (o/e) 0.94, 90% interval 0.8 to 1.11.
Homologues: Orthologues: chimpanzee TNFAIP8L3 (100% identical), macaque TNFAIP8L3 (99% identical), dog TNFAIP8L3 (97% identical), rabbit TNFAIP8L3 (97% identical), mouse Tnfaip8l3 (91% identical), pig TNFAIP8L3 (90% identical), rat Tnfaip8l3 (86% identical), guinea pig TNFAIP8L3 (84% identical), tropical clawed frog tnfaip8l3 (75% identical), zebrafish tnfaip8l3 (70% identical), Drosophila melanogaster sigmar (39% identical). Paralogues in human: TNFAIP8 (56% identical), TIPE1 (50% identical), TIPE2 (50% identical).
Diseases named in the same sentence as TIPE3 in open-access papers:
TIPE3 is named in the same sentence as 30 diseases in open-access papers, as found by Europe PMC text mining. Sharing a sentence is not in itself a finding about the gene and the disease. The quoted sentences say what the papers report.
lung carcinoma (8 papers, 2018 to 2025). "In this study, we considered the TIPE3 protein, which is defined as a transfer protein for secondary lipid messengers that is upregulated in human lung cancer tissues." (PMID 37375246, 2023). "Researches have discovered that the TIPE3 expression elevated in esophageal cancer, lung cancer, breast cancer, OvCa, and glioblastoma." (PMID 37256178, 2023). "TIPE3 is highly expressed in most human tumor cell lines, such as lung cancer cell line NCI-H727, bladder cancer cell line T24, and colon adenocarcinoma cell line HT-29, but with a low expression in the gastric cancer cell line." (PMID 36755222, 2023). "Similar to lung cancer tissues, TIPE3 expression was observed in cytoplasm as well as the inner side of plasma membrane in both H1975 and A549 cells." (PMID 29510688, 2018). "TIPE3 expression was found in normal human lung tissues, and markedly increased in human lung cancer tissues." (PMID 29510688, 2018). "TIPE3 was found to be upregulated in lung cancer, esophageal cancer, cervical cancer, and colon adenocarcinoma." (PMID 30217224, 2018). "Using two NSCLC cell lines A549 and H1975, we showed that TIPE3 was highly expressed in plasma membrane of the lung cancer cells with long pseudopodia, particularly in the position of protrusion." (PMID 29510688, 2018). "Further immunofluorescence confirmed that TIPE3 displaying dot-like fluorescence signals mainly gathered in the plasma membrane, indicating that exogenous TIPE3 located in plasma membrane is crucial for the proliferation and migration of lung cancer cells." (PMID 29510688, 2018). "To clarify the effects of TIPE3 on the proliferation and migration of lung cancer cells, we used siTIPE3 to knock down the expression of endogenous TIPE3 in H1975 cells, which expressed higher level of TIPE3 than A549 cells." (PMID 29510688, 2018). "TIPE3 enhances the progression of lung cancer by activating Akt/mTOR, NF-κB, and STAT-3 signaling." (PMID 40280943, 2025). "At the same time, it is significantly up-regulated in lung cancer, esophagus cancer, cervical cancer, and colon cancer; it was found that TIPE3 overexpression significantly increased the migration, invasion, and proliferation of MCF-7 and MDA-MB-231 tumor cells in human breast cancer cell lines." (PMID 36755222, 2023). "However, we previously identified that TIPE3 was hypermethylated and downregulated in several cancers, including bladder cancer, colon and rectal cancer, lung cancer, prostate cancer, and HNSC in TCGA." (PMID 37024453, 2023). "So, in the present study, TIPE3 on plasma membrane may be involved in cell motility and contribute to the growth and migration of lung cancer cells." (PMID 29510688, 2018). "TIPE3 (TNFAIP8L3), a transfer protein for lipid second messengers, is upregulated in human lung cancer tissues." (PMID 29510688, 2018). "Yet, TIPE3 promoted cell progression was not relied on the TH domain but its unique NT region, truncating which induced tumor suppression effect in lung carcinoma cells, bladder carcinoma cells, and colorectal adenocarcinoma cells." (PMID 37024453, 2023). "Human TIPE3 is highly expressed in lung cancer tissues compared with adjacent non-cancer tissues, indicating the possible involvement of TIPE3 in lung tumorigenesis." (PMID 29510688, 2018). "We found that TIPE3 expression was significantly downregulated in six cancer types, including BLCA (bladder cancer), CESC (cervical cancer), COADREAD (colon and rectal cancer), HNSC (head and neck cancer), LUNG (lung cancer),and PRAD (prostate cancer)." (PMID 30217224, 2018). "The most popular lung cancer is non-small cell lung cancer (NSCLC) with high incidences and low survival rates, while the roles of TIPE3 in NSCLC remain largely unknown." (PMID 29510688, 2018).
breast carcinoma (7 papers, 2017 to 2025). "In breast cancer cells, the inhibition of TIPE3 expression significantly decreased uPA expression through activation of the AKT/NF-κB pathway." (PMID 39248711, 2024). "Based on these characteristics, full-length TIPE3 had been confirmed to promote several cancer progression, including cervical cancer, breast cancer, and stomach cancer." (PMID 37024453, 2023). "In summary, our findings demonstrated that TIPE3 protein was upregulated in breast cancer tissues and positively correlated to invasion and metastasis of human breast cancer cells by activating AKT and NF-κB signaling pathways." (PMID 28388580, 2017). "In order to determine the roles of TIPE3 in human breast cancer, we examined the expression of TIPE3 protein in 96 human breast cancer samples and microarrays by immunohistochemistry." (PMID 28388580, 2017). "Our results showed that TIPE3 was upregulated markedly in malignant tissues of breast cancer compared to adjacent tissues from the same patients." (PMID 28388580, 2017). "We found that TIPE3 was highly expressed in breast cancer tissues and positively correlated with HER2 expression." (PMID 28388580, 2017). "Taken together, these data demonstrate that TIPE3 promotes proliferation, migration and invasion of breast cancer cells by activating AKT and NF-κB pathways." (PMID 28388580, 2017). "To examine the functions of TIPE3 in tumorigenesis and metastasis in vivo, we established breast cancer subcutaneous xenograft and lung metastasis models in nude mice." (PMID 28388580, 2017). "It has been reported that TIPE3 could accelerate the metastasis of breast cancer by activating AKT and NF-kB signaling pathways." (PMID 40904408, 2025). "TNFAIP8L3 (TNF alpha-induced protein 8 like 3, also known as TIPE3), a transfer protein of phosphoinositide second messengers, was detected to be significantly upregulated in breast cancer tissues (especially invasive or metastasized type) as compared with adjacent nontumor tissues." (PMID 32149080, 2020). "Importantly, a positive correlation was found between the levels of TIPE3 expression and the pathological grading in breast cancer samples." (PMID 28388580, 2017). "We report here that human TIPE3 could promote proliferation, invasion, and metastasis of breast cancer cells, and may serve as a potential biomarker and therapeutic target for advanced breast cancer." (PMID 28388580, 2017). "Similarly, the staining of TIPE3 protein was stronger in lymph node metastatic breast cancer cells than that in DCIS or invasive ductal cancer cells from the same patients." (PMID 28388580, 2017). "Importantly, TIPE3 knockdown in breast cancer cells inhibited cell proliferation, migration, and invasion in vitro, whereas TIPE3 overexpression had the opposite effect." (PMID 28388580, 2017). "Finally, TIPE3 regulates proliferation, migration and invasion in breast cancer cells by activating AKT and NF-κB pathways." (PMID 28388580, 2017). "In mice, TIPE3 expression significantly promoted the metastasis of breast cancer cells." (PMID 28388580, 2017). "Additionally, the level of TIPE3 protein was positively correlated with the level of human epidermal growth factor receptor 2 (HER-2), and TIPE3 expression was significantly higher in high-invasive breast cancer cell lines than that in low-invasive cell lines." (PMID 28388580, 2017). "In addition, we also found that the expression level of TIPE3 is higher in HER2-positive breast cancer cells (SKBR3) than that in HER2-negative breast cancer cells (MCF-7 and MDA-MB-231)." (PMID 28388580, 2017). "More importantly, TIPE3 promoted the migration and invasion of human breast cancer by activating p-AKT and NF-κB pathways, and TIPE3 could accelerate the metastasis of human breast cancer cells in nude mice." (PMID 28388580, 2017).
breast carcinoma (continued). "The inhibitors of AKT and NF-κB pathways, such as CAPE and LY294002, could block the enhanced proliferation, colony formation and migration of breast cancer cells induced by overexpressed TIPE3." (PMID 28388580, 2017). "TIPE3 was able to promote significantly the proliferation of human breast cancer cells." (PMID 28388580, 2017). "Firstly, we found that TIPE3 could promote the proliferation of breast cancer cells." (PMID 28388580, 2017). "Importantly, the expression of TIPE3 was positively correlated with pathological grading and HER2 expression, suggesting that elevated expression of TIPE3 may be correlated with the increase of malignancy degree in breast cancer tissue." (PMID 28388580, 2017). "Furthermore, TIPE3 could accelerate breast cancer cell migration and invasion both in vitro and in vivo." (PMID 28388580, 2017). "Interestingly, blocking PI3K-AKT pathway by LY294002 largely abolished the activation of NF-κB induced by TIPE3 overexpression, suggesting that TIPE3 might activate NF-κB through AKT pathway during breast cancer development." (PMID 28388580, 2017). "However, the role of TIPE3 in human breast cancer remains to be established." (PMID 28388580, 2017). "Interestingly, the elevation of p-IkBα and p-P65 induced by overexpressed TIPE3 was also largely blocked by LY294002, suggesting that TIPE3 might activate NF-κB pathway through AKT pathway in breast cancer cells." (PMID 28388580, 2017). "TIPE3 protein promotes breast cancer metastasis by activating AKT and NF-κB signaling pathways, suggesting that TIPE3 may be involved in cancer cell survival." (PMID 30586922, 2018). "PI3K-AKT signaling pathway regulates tumorigenesis and metastasis of breast cancer However, the role of TIPE3 in the migration and invasion of breast cancer has never been examined." (PMID 28388580, 2017). "We report here that TIPE3 protein was significantly upregulated in human breast cancer tissues as compared with adjacent non-tumor tissues from the same patients." (PMID 28388580, 2017).
colorectal cancer (4 papers, 2023 to 2025). A primary or metastatic malignant neoplasm that affects the colon or rectum. "Thus, TIPE3 enhances cellular resistance to colorectal cancer drugs by inhibiting the apoptosis of CRC cells, promoting autophagy, and alleviating drug-induced cellular injury." (PMID 40280943, 2025). "Here, we found that TIPE3 overexpression inhibited apoptosis in CRC cells while promoting cell autophagy, alleviating drug-induced cell injury, and enhancing cellular resistance to colorectal cancer drugs." (PMID 40280943, 2025).
esophageal cancer (4 papers, 2018 to 2024). A primary or metastatic malignant neoplasm involving the esophagus. "TNFAIP8-like 3 (TIPE3): The biological role of TIPE3 is still unknown; only a few studies have shown that TIPE3 is an oncogenic molecule and that increased levels of TIPE3 are present in cervical, colon, lung and esophageal cancers." (PMID 30586922, 2018).
gastric cancer (4 papers, 2018 to 2024). A primary or metastatic malignant neoplasm involving the stomach. "By Agilent Whole Human Genome Oligo Microarray for global human gene expression analysis, we found that among TIPE family, the levels of TIPE1 and TIPE3 were decreased in poorly cohesive gastric carcinoma tissues compared with adjacent non‐tumour tissues." (PMID 28994231, 2018). "In gastric cancer, the overexpression of TIPE3 promoted GC cell growth and metastasis by upregulating the phosphorylation of PI3K and AKT." (PMID 38727307, 2024).
glioblastoma (4 papers, 2023 to 2025). The most malignant astrocytic tumor (WHO grade IV). "The aberrant expression of TIPE3 has been identified in a variety of neoplasms, including nasopharyngeal cancer, gastric carcinoma, glioblastoma, and lung cancer." (PMID 40904408, 2025). "While TIPE3 promotes the proliferation of glioblastoma cells via inhibiting p38/MAPK signaling." (PMID 40904408, 2025). "Meanwhile, in human glioblastoma (GBM), overexpressed TIPE3 inhibits p38 phosphorylation and blocks p38 nuclear translocation, leading to the negative regulation of the p38 MAPK pathway and resulting in GBM cell survival." (PMID 36755222, 2023).
colon adenocarcinoma (3 papers, 2018 to 2024). "To further validate the effects of K784-8160 on cancer cells, we performed flow cytometry to enumerate the number of -colon adenocarcinoma cells (HT-29 and LoVo) expressing TIPE3 highly in the culture." (PMID 38727307, 2024).
lymph node metastasis (2 papers, 2023). "Patients with late-stage (TNM III-IV) or with lymph node metastasis patients had lower TIPE3 mRNA levels than those with early-stage (TNM I-II) or without lymph node metastasis ones, respectively." (PMID 37024453, 2023). "The expression of TIPE3 has a positive correlation with tumor size, pathological stage, lymph node metastasis and other malignant clinicopathological characteristics." (PMID 37256178, 2023).
nasopharyngeal carcinoma (2 papers, 2018 to 2023). A carcinoma arising from the nasopharyngeal epithelium. "Our previous genome-wide methylation profile showed that tumor necrosis factor-alpha-induced protein 8 like 3 (TIPE3) was hypermethylated in nasopharyngeal carcinoma (NPC)." (PMID 30217224, 2018). "For the first time, we found that overexpressing full-length TIPE3 acted as a tumor suppressor and suppressed nasopharyngeal carcinoma (NPC) cells progression in vitro and in vivo." (PMID 37024453, 2023).
pancreatic cancer (2 papers, 2025). "For example, TIPE2 suppresses tumor growth by directly binding to RAC1, whereas TIPE3 promotes pancreatic cancer progression in a RAC1-dependent manner." (PMID 40904408, 2025). "In pancreatic cancer, TIPE3 promotes tumor progression by upregulating RAC1." (PMID 40280943, 2025). "It has been reported that TIPE3 may promote tumor progression via increasing RAC1 expression in pancreatic cancer." (PMID 40904408, 2025).
invasive ductal carcinoma (1 paper, 2017). "The level of TIPE3 protein in invasive ductal carcinoma was significant higher than that in ductal carcinoma in situ (DCIS), and the level of TIPE3 in lymphatic metastasized carcinoma was higher than that in invasive ductal carcinoma from the same patients." (PMID 28388580, 2017). "Importantly, the staining of TIPE3 protein in invasive ductal carcinoma was stronger than in DCIS from the same patients (Figure 1B1–1B3, P = 0.007)." (PMID 28388580, 2017). "Furthermore, TIPE3 expression in the lymphatic metastasized carcinoma was stronger than that in invasive ductal carcinoma from the same patients (Figure 1D1 and 1D2, 1E1 and 1E2, P = 0.032)." (PMID 28388580, 2017). "Interestingly, the levels of TIPE3 staining in invasive ductal carcinoma were significant higher than that in DCIS from the same patients." (PMID 28388580, 2017).